LRRC3B (leucine rich repeat containing 3B)
Synonyms: LRP15
Tractability: Antibody: UniProt predicts a signal peptide or a membrane-spanning region; its Gene Ontology location is reachable by antibodies, with medium confidence.
Gene: Protein-coding gene on chromosome 3 (26,622,772 to 26,717,537, forward strand). Ensembl gene ENSG00000179796.
Subcellular location: Membrane
Gene Ontology:
Molecular function: protein binding; signaling receptor activity
Cellular component: plasma membrane; membrane
Genetic constraint (gnomAD): Loss-of-function variants: 2 observed, 13.55 expected, observed/expected ratio (o/e) 0.15, 90% interval 0.059 to 0.47. The upper end of that interval is the gene's LOEUF score, 0.47, which puts it in group 2 of 6, group 1 being the genes least tolerant of losing a copy. Missense variants: 189 observed, 336.31 expected, observed/expected ratio (o/e) 0.56, 90% interval 0.5 to 0.63. Synonymous variants: 132 observed, 127.91 expected, observed/expected ratio (o/e) 1.03, 90% interval 0.89 to 1.19.
Homologues: Orthologues: chimpanzee LRRC3B (100% identical), dog LRRC3B (100% identical), guinea pig LRRC3B (100% identical), macaque LRRC3B (100% identical), pig LRRC3B (100% identical), mouse Lrrc3b (99% identical), rabbit LRRC3B (99% identical), rat Lrrc3b (99% identical), tropical clawed frog lrrc3b (92% identical), zebrafish lrrc3b (66% identical). Paralogues in human: LRRC3 (44% identical), LRRC3C (35% identical), VASN (23% identical), RXFP2 (20% identical), TLR6 (19% identical), TLR8 (19% identical), TLR7 (17% identical), IGFALS (17% identical), RXFP1 (17% identical), TLR1 (17% identical), TLR10 (17% identical), TLR3 (16% identical), and 10 more.
Diseases named in the same sentence as LRRC3B in open-access papers:
LRRC3B is named in the same sentence as 12 diseases in open-access papers, as found by Europe PMC text mining. Sharing a sentence is not in itself a finding about the gene and the disease. The quoted sentences say what the papers report.
gastric cancer (4 papers, 2013 to 2023). A primary or metastatic malignant neoplasm involving the stomach. "Interestingly, aberrant DNA methylation of LRRC3B is associated with several types of cancer, including gastric cancer, COAD, BRCA, lung cancer, kidney cancer, ovarian cancer (OV), and prostate cancer (PRCA)." (PMID 36798137, 2023). "LRRC3B acts as tumor suppressor gene, and the expression of LRRC3B in gastric cancer, renal cancer, colorectal cancer (COAD), lung cancer, and breast cancer (BRCA) tissue is lower than in adjacent normal tissue." (PMID 36798137, 2023).
breast carcinoma (3 papers, 2016 to 2023). "Relationships between LRRC3B polymorphisms and breast cancer risk according to the stratification by age." (PMID 34178643, 2021). "Relationships between LRRC3B rs1907168 polymorphism and breast cancer risk." (PMID 34178643, 2021). "The association between LRRC3B polymorphisms and clinical features of breast cancer." (PMID 34178643, 2021). "LRRC3B levels were measured by qPCR in H1299 (lung cancer cell) and Hs578T (breast cancer cell) cells, but were very low and barely detected." (PMID 36798137, 2023). "LRRC3B gene, as a tumor suppressor gene was involved in the development and progress of breast cancer (BC)." (PMID 34178643, 2021). "Study of human cancer microarray showed LRRC3B was downregulated in breast cancer and colorectal cancer, which declares that LRRC3B takes part in tumor formation." (PMID 27118644, 2016). "Additionally, LRRC3B is down-regulated in non-small-cell lung, head and neck, gastric and breast cancers, suggesting LRRC3B involvement in carcinogenesis." (PMID 34178643, 2021). "Furthermore, over-expression of LRRC3B was reported to inhibit cell cycle proliferation, invasion, and progression of lung and breast cancer cells, suggesting that LRRC3B may be a useful marker for the diagnosis and prognosis of BRCA and non-small cell lung cancer (NSCLC)." (PMID 36798137, 2023).
lung carcinoma (2 papers, 2016 to 2023). "This study is to investigate the expression of LRRC3B in lung cancer cell lines and the influence of LRRC3B during cell proliferation, invasion and cell cycle." (PMID 27118644, 2016). "During 4 of 9 lung cancer cell lines, the expression of LRRC3B is downregulated compared with normal epithelial cells." (PMID 27118644, 2016). "LRRC3B siRAN was transfected in lung cancer cell line H3255, and then the effect of LRRC3B on cell proliferation, invasion and cell cycle was analyzed." (PMID 27118644, 2016). "LRRC3B expression downreguated in lung cancer cell lines and LRRC3B could inhibit lung cancer cell proliferation, invasion and cell cycle progress." (PMID 27118644, 2016). "We performed authentication testing of the correlation between LRRC3B expression and infiltration of CD4+/CD8+ T cell, using multiplexed fluorescence immunohistochemistry (mIHC), in the lung cancer tissue array." (PMID 36798137, 2023).
renal carcinoma (2 papers, 2016 to 2023). A carcinoma arising from the epithelium of the renal parenchyma or the renal pelvis. "Hypermethylation on cfDNA was detected for the LRRC3B (74.1%), APC (51.9%), FHIT (55.6%), and RASSF1 (62.9%) genes in patients with renal cancer." (PMID 27725787, 2016). "A high level of LRRC3B hypermethylation was noted not only in RCC patients (74%), but also in healthy donors (33%) in our study, questioning the use of this gene for the diagnosis of renal cancer on cfDNA." (PMID 27725787, 2016). "Large-scale NotI-microarray analyses of genetic and epigenetic alterations in the genes of chromosome 3 in RCC revealed that leucine-rich repeats containing 3B (LRRC3B) and Von Hippel-Lindau (VHL) genes possess the highest frequency of deletions and/or methylations in renal carcinoma." (PMID 27725787, 2016).
bladder cancer (1 paper, 2023). "Leucine-rich repeat (LRR)-containing 3B (LRRC3B) inhibits proliferation and invasion by targeting β-catenin, cyclin D1, and c-Myc in bladder cancer cells; nevertheless, its expression has been observed to be substantially downregulated in BCa." (PMID 37542643, 2023).
head and neck cancer (1 paper, 2016). A primary or metastatic malignant neoplasm affecting the head and neck. "Increased methylation of the LRRC3B gene promoter was confirmed in samples of clear cell RCC and colorectal, head, and neck cancer." (PMID 27725787, 2016).
cancer (7 papers, 2014 to 2023). A tumor composed of atypical neoplastic, often pleomorphic cells that invade other tissues. "A high silencing score was significantly associated with immune inhibition, low expression of LRRC3B, poor patient survival, and activation of cancer-related pathways." (PMID 36798137, 2023). "Moreover, overexpression of LRRC3B was associated with better survival in several cancers, such as BLCA, BRCA, LUAD, KIRC, and LICH." (PMID 36798137, 2023). "Our data suggest that LRRC3B is a putative tumor suppressor gene across multiple cancers, including in BRCA, bladder urothelial carcinoma (BLCA), kidney renal clear cell carcinoma (KIRC), skin cutaneous melanoma (SKCM), lung adenocarcinoma (LUAD), and COAD." (PMID 36798137, 2023). "Consistently, our results also showed that the methylation level of LRRC3B is significantly higher in cancer tissues than in the normal adjacent tissues." (PMID 36798137, 2023). "Our results suggest that the expression of LRRC3B was repressed in most of TCGA cancers, especially at higher tumor stages." (PMID 36798137, 2023). "In these nine cancers, Spearman correlation analysis showed that the silencing score was negatively correlated with LRRC3B mRNA expression, fully consistent with the inferred inhibition of LRRC3B suggested by the DNA methylation levels." (PMID 36798137, 2023). "First, we explore a tumor suppressor role for LRRC3B in different cancer types by differential analysis, immune cell infiltration, and predictive power of relative drugs." (PMID 36798137, 2023). "Altogether, these findings strongly suggest that LRRC3B has tumor suppressor qualities and is associated with slower tumor progression, better tumor staging, and reduced metastasis, and could serve as early biomarker for cancer detection, staging, and follow-up." (PMID 36798137, 2023). "To obtain a comprehensive picture of the DNA methylation levels of LRRC3B, we next performed an unsupervised consensus clustering of all 25 CpG sites in the nine cancers that were related to patients’ survival." (PMID 36798137, 2023). "The difference of LRRC3B protein expression between normal lung epithelial cells and cancer cells was measured by immunoblotting." (PMID 36798137, 2023). "Our comprehensive analysis demonstrated the potential role of LRRC3B in the anti-tumor microenvironment, clinicopathological features of cancer, and disease prognosis." (PMID 36798137, 2023). "LRRC3B has an essential role in tumorigenesis and cancer progression, and LRRC3B is involved in plant and animal immunity, hormone-receptor interactions, cell adhesion, signal transduction, regulation of gene expression, and apoptosis." (PMID 36798137, 2023). "We evaluated a number of methylation profiles to assess the effects of LRRC3B silencing on cancer immunotherapy." (PMID 36798137, 2023). "Here, we assess the effects and potential tumor microenvironmental actions of LRRC3B in 33 cancer types from the TCGA databases." (PMID 36798137, 2023). "LRRC3B expression is downregulated in many kinds of malignant tumors and it is regarded as tumor inhibition protein." (PMID 27118644, 2016). "A number of microarray expression profiling studies have shown that LRRC3B is downregulated in various cancers suggesting that LRRC3B is involved in carcinogenesis." (PMID 26198328, 2015). "Based on experiments using transformed carcinoma cell lines, a role in the suppression of cell proliferation has been suggested for LRRC3B." (PMID 26484354, 2015). "MDSCs are reported to exert immunosuppressive functions in tumor immunotherapy, and the overexpression of LRRC3B may a potential approach to enhance anti-PD-L1 cancer immunotherapy, although this requires further validation." (PMID 36798137, 2023). "LRRC3B promoter methylation has significant tumor specificity and may be an early prognostic biomarker to predict immune response in cancers." (PMID 36798137, 2023).
cancer (continued). "Furthermore, through analyzing data from TCGA, we found that LRRC3B mRNA expression is significantly lower in tumors of multiple cancer types compared with their corresponding adjacent normal tissues." (PMID 36798137, 2023). "In conclusion, we report that LRRC3B may exert anti-tumor effects in multiple cancer types, and may be an essential actor in the tumor microenvironment to determine the response to immune checkpoint inhibitors." (PMID 36798137, 2023). "However, LRRC3B showed a low specificity as a marker of cancer, since it was methylated in 5 out of 15 (33.3%) healthy donors." (PMID 27725787, 2016). "Additionally, it is unknown whether LRRC3B DNA methylation levels can serve as a marker to predict response to cancer therapy, especially for anti-PD-1/PD-L1 treatment." (PMID 36798137, 2023). "LRRC3B DNA methylation levels may be a marker that can be used for cancer diagnosis and prognosis." (PMID 36798137, 2023). "Using bisulfite treatment followed by MS-PCR we detected methylation of the LRRC3B, APC, FHIT, and RASSF1 genes in the cfDNA of cancer patients." (PMID 27725787, 2016). "We conducted pearson correlation analysis of LRRC3B and tumor microenvironment (TME) in pan-cancer." (PMID 36798137, 2023). "These genes include tumor suppressors or candidates (VHL, CTDSPL, LRRC3B, ALDH1L1, and EPHB1) and genes that were not previously considered as cancer-associated (e.g., LRRN1, GORASP1, FGD5, and PLCL2)." (PMID 24977159, 2014).
tumor (7 papers, 2014 to 2025). "LRRC3B encodes a leucine-rich repeat protein that inhibits tumor proliferation, colony formation, and invasion." (PMID 36798137, 2023). "LRRC3B expression associated with less tumor invasion, less severe tumor stage, and decreased metastasis." (PMID 36798137, 2023). "We also investigated the potential associations of LRRC3B polymorphisms with clinicopathological characteristics of BC, including tumor size, lymph node metastasis, clinical stage, the status of ER, PR, Her-2, and Ki67." (PMID 34178643, 2021). "We further evaluated the association of LRRC3B polymorphisms with clinical features of BC, including tumor size, lymph node metastasis, clinical stage, the status of ER, PR, Her-2, and Ki67." (PMID 34178643, 2021). "Our findings showed LRRC3B polymorphisms were associated with tumor size and PR/Ki-67 status, which might act as predictors for BC occurrence and development." (PMID 34178643, 2021). "Formerly, the expression of LRRC3B was reduced in BC tissues and associated with tumor grade of BC." (PMID 34178643, 2021). "Haploinsufficiency of chromosome 3 tumor suppressors such as Lrrc3b (fold change of −2.69 in STOSE cells) may underlie transformation." (PMID 24672774, 2014). "To further explore the role of LRRC3B in tumor progression, we compared the expression levels of LRRC3B based on tumor stage." (PMID 36798137, 2023). "The leucine rich repeat containing 3B (LRRC3B) gene is a tumor suppressor gene involved in the anti-tumor immune microenvironment." (PMID 36798137, 2023). "We found that LRRC3B expression was lower at higher tumor stages in LUAD, MESO, LUSC, and THCA, and was increased in STAD and PAAD." (PMID 36798137, 2023). "To complete a comprehensive analysis of LRRC3B, we further evaluated the differences of tumor immune infiltration across deep deletion, arm-level deletion, arm-level gain, and high amplification, compared with normal tissue." (PMID 36798137, 2023). "We found that copy number variation of LRRC3B decreased the infiltration of immune cells and possibly promoted tumor progression." (PMID 36798137, 2023). "LRRC3B has many biological functions, such as regulation of cell proliferation, cell cycle progression, and tumor escape from immune surveillance." (PMID 36798137, 2023). "And, we evaluated the differential expression of LRRC3B according to tumor stage, overall survival, and characteristics of the tumor microenvironment." (PMID 36798137, 2023). "Having established the link between silencing score and LRRC3B expression, we explored immunity based on methylation levels to further show that LRRC3B plays a crucial role in the tumor microenvironment." (PMID 36798137, 2023). "As a tumor suppressor gene, LRRC3B exerts tumor suppressor activity through immune responses." (PMID 36798137, 2023). "These analyses further illustrate the anti-tumor effects of LRRC3B in multiple cancers." (PMID 36798137, 2023). "This provides strong evidence that LRRC3B might play an essential role in tumor inhibition facilitated through CD4+/CD8+ T cells." (PMID 36798137, 2023). "However, no studies have yet systematically explored the protective role of LRRC3B methylation in tumor progression and immunity." (PMID 36798137, 2023). "To better understand the molecular relationship between expression of LRRC3B and tumor immunity, we calculated the Pearson correlation of LRRC3B expression with a panel of immunomodulators, including chemokines, immunostimulators, and MHC modules, that are crucial in immunotherapy." (PMID 36798137, 2023). "Our findings also provided evidence that hypermethylation of the LRRC3B promoter may facilitate tumor escape from immune surveillance." (PMID 36798137, 2023). "However, no studies have yet systematically explored the protective role of LRRC3B in tumor progression and immunity." (PMID 36798137, 2023). "More importantly, tumor escape from immune surveillance was reported following silencing of LRRC3B." (PMID 36798137, 2023).
tumor (continued). "In addition, LRRC3B gene was down-regulated in BC tumor and had a poor prognosis in BC in in silico analysis." (PMID 34178643, 2021). "Thus, we explored the tumor suppressor role of LRRC3B in multiple cancers." (PMID 36798137, 2023). "TNF-alpha signaling via NF-kB, IL6/JAK/STAT3 signaling, PI3K/AKT/mTOR signaling, MYC targets v2, TGF-beta signaling, and Kras signaling were mostly negatively correlated with LRRC3B expression, consistent with silencing of LRRC3B in tumor tissue, which may result in carcinogenesis." (PMID 36798137, 2023). "Several studies have revealed that LRRC3B could be a tumor suppressor in carcinogenesis." (PMID 34178643, 2021). "Several members, such as LRRC4 and LRRC3B, are either absent or significantly downregulated in various malignancies, suggesting their roles as tumor suppressors." (PMID 40388100, 2025). "We found that genomic instability scores were correlated with hypermethylation of LRRC3B, which suggested that hypomethylation of LRRC3B in BRCA and NSCLC could prevent tumor escape from immune surveillance." (PMID 36798137, 2023).
metabolic disease (1 paper, 2023). A congenital disorder (due to inherited enzyme abnormality) or acquired (due to failure of a metabolically important organ) disorder resulting from an abnormal metabolic process. "A gene and disease network interaction analysis revealed that LRRC3B was associated with metabolic diseases, cell proliferation, immune system, and multiple cancers." (PMID 36798137, 2023).
LRRC3B also shares sentences with these, for which no sentence is quoted: colorectal cancer (2 papers); head and neck squamous cell carcinoma (1); lymph node metastasis (1).